GAPDH (glyceraldehyde-3-phosphate dehydrogenase)
Diseases named in the same sentence as GAPDH in open-access papers (continued):
Sharing a sentence is not in itself a finding about the gene and the disease.
chronic myelocytic leukemia (1 paper, 2012). "As a result, the expression level of MRP4 was extremely high (151 copies of transcript/103 copies of GAPDH) by comparison with those of other transporters in the chronic myelocytic leukemia cell line KU812." (PMID 23181130, 2012).
clear cell renal carcinoma (1 paper, 2017). A malignant epithelial neoplasm of the kidney characterized by the presence of lipid-containing clear cells within a vascular network. "Ppia, was optimal candidate (along with PRS13) in clear cell renal carcinoma as compared to classical genes such as ACTB, GAPDH, 18s or B2m." (PMID 28591185, 2017).
coeliac disease (1 paper, 2014). "RT-PCR evaluation in matched biopsies also demonstrated marked increase of IL-6 mRNA in coeliac disease compared to controls, with mean expression density 508 vs 68/mm2, normalised to GAPDH 0.68 vs 0.05 (p<0.014)." (PMID 25198673, 2014).
colon adenoma (1 paper, 2010). An adenoma that arises from the colon. "We conducted qRT-PCR analysis on these genes along with two reference genes β-actin and GAPDH, with 12 matched colon adenomas and normal tissue samples from several ApcMin/+ mice." (PMID 20707908, 2010).
colorectal adenoma (1 paper, 2012). An adenoma that arises from the colon or rectum. "GAPDH RNA transcripts were detectable in all 60 plasma samples tested and moderately higher GAPDH RNA levels were observed in plasma specimens from patients diagnosed with colorectal adenomas or cancer compared to healthy donors (not significant, p values >0.05)." (PMID 22276102, 2012).
Crohn disease (1 paper, 2023). A gastrointestinal disorder characterized by chronic inflammation involving all layers of the intestinal wall, noncaseating granulomas affecting the intestinal wall and regional lymph nodes, and transmural fibrosis. "The authors observed that oxidation of GAPDH active-site thiols and subsequent inhibition of enzyme activity were consistent observations in preparations of CECs from the inflamed mucosa of Crohn’s disease." (PMID 37512550, 2023).
cryptosporidiosis (1 paper, 2021). Intestinal infection with organisms of the genus Cryptosporidium. "Host proteins involved in energy pathways and Lactobacillus glyceraldehyde-3-phosphate dehydrogenase were upregulated during cryptosporidiosis." (PMID 34208228, 2021).
cystitis (1 paper, 2016). Inflammation of the urinary bladder. "We also observed that the TRPA1 had much more expression in the cystitis mucosa than the normal via AGE and the fat tissue did not express TRPA1 mRNA, although they expressed GAPDH mRNA." (PMID 27315798, 2016).
deafness (1 paper, 2025). An inherited or acquired condition characterized by the complete loss of the ability to hear from one or both ears. "In addition to GAPDH and TCF4, SLC4A11 was chosen as a comparison gene because of its confirmed association with congenital hereditary endothelial dystrophy (CHED) accompanied by perceptive deafness." (PMID 40244234, 2025).
disseminated candidiasis (1 paper, 2016). Systemic candidiasis occurs when Candida yeast enters the bloodstream and may spread (becoming disseminated candidiasis) to other organs, including the central nervous system, kidneys, liver, bones, muscles, joints, spleen, or eyes. "The protein, however, is apparently a poor immunogen, since vaccination with GAPDH or exposure of mice to antibodies against GAPDH did not impact the outcome of disseminated candidiasis." (PMID 27458437, 2016).
ductal carcinomas (1 paper, 2022). "To investigate if LaNt α31 expression is linked to proliferation, we used inhibited cell division using mitomycin c in two widely used cell lines derived from malignant ductal carcinomas, MCF7 and MDA-MB-231, then quantified LAMA3LN1 transcript abundance using RT-qPCR normalised to GAPDH and RPLP0." (PMID 35231053, 2022).
endometriosis (1 paper, 2024). The growth of functional endometrial tissue in anatomic sites outside the uterine body. "Moreover, cyto-hub gene analysis revealed that CSNK2A1, CSNK2A2, TOP1, PRKACA, RBM39 (plasma), ALB, ACTB, GAPDH, FN1, APOA1 (serum), S100-A9, CXCL1, IL1RN, CSTA, S100-A8 (menstrual blood) and THBS1, ALB, CD44, ANXA2, and LUM (urine) were the top 5 proteins expressed in women with endometriosis." (PMID 39061077, 2024).
endotoxemia (1 paper, 2012). "We have detected elevated level of caspase-3 protein in the acini isolated from animals subjected to the endotoxemia in the infancy due to increasing doses of LPS (5, 10 or 15 mg/kg/day × 5 days) with the ratio of caspase-3/GAPDH reaching 113.0 ± 0.4." (PMID 22685683, 2012).
enteritis (1 paper, 2025). Inflammation of the small intestine. "Although no obvious trend was observed in the visual bands, one-way ANOVA of the ratio of the target protein grayscale value to the internal reference protein GAPDH grayscale value revealed significant differences in the target protein among normal individuals, enteritis patients, and IBD patients." (PMID 40830794, 2025).
esophageal tumors (1 paper, 2025). "Overexpression of GAPDH is a characteristic associated with accelerated proliferation in many tumors, such as breast, lung, pancreatic, and esophageal tumors, suggesting GAPDH as an attractive target for the treatment of tumors." (PMID 40612109, 2025).
Fabry disease (1 paper, 2021). Fabry disease (FD) is a progressive, inherited, multisystemic lysosomal storage disease characterized by specific neurological, cutaneous, renal, cardiovascular, cochleo-vestibular and cerebrovascular manifestations. "However, if we were to choose GAPDH (Fabry vs Normal FC 0.49) as RG we would have to conclude that PON1 is overexpressed in Fabry’s disease, as the GAPDH gene itself is significantly decreased in patients with Fabry disease." (PMID 34882702, 2021). "The commonly used RG GAPDH was differentially expressed only in 3/8 Fabry disease datasets." (PMID 34882702, 2021).
fibrosarcoma (1 paper, 2021). A malignant mesenchymal fibroblastic neoplasm affecting the soft tissue and bone. "Results from dot blot and western blot analysis demonstrated that GM1 ganglioside, and TSG101, HSC70 and GAPDH proteins were contained in exosomes from the WEHI-164 fibrosarcoma cell line." (PMID 33497388, 2021).
gastric tumorous (1 paper, 2013). "The expression levels of GP73 relative to GAPDH were much lower in gastric tumorous tissues (0.259 ± 0.308) than that in non-tumorous mucosal tissues (0.584 ± 0.523; P<0.01)." (PMID 23742050, 2013).
glucose metabolism disorders (1 paper, 2022). "Given that the proteins PFKM, GAPDH, ACO2, and MDH2 have rate-limiting effects on aerobic oxidative metabolism, the decreased expression is consistent with the results of glucose metabolism disorders in diabetic patients." (PMID 36187097, 2022).
gram-positive bacterial infections (1 paper, 2011). Infections caused by bacteria that retain the crystal violet stain (positive) when treated by the gram-staining method. "GAPDH in the outer membrane is highly antigenic, and is considered to be a strong vaccine candidate to counter not only Gram-negative but also Gram-positive bacterial infections." (PMID 21408115, 2011).
head and neck cancer (1 paper, 2017). A primary or metastatic malignant neoplasm affecting the head and neck. "Data analysis and ranking of the top 5 HKGs using geNorm and Normfinder identified UBC, TBP, IPO8, TFRC, GAPDH in head and neck cancer; TBP, IPO8, GUSB, UBC in lung and TBP, IPO8, TFRC, GUSB, HMBS in pancreas to be stable." (PMID 28262749, 2017). "Unlike head and neck cancer cell lines, TBP was stably expressed in A549 and NCI-H226 across all IR dose treatment groups while PP1A, GAPDH and B2M expression was exclusively expressed at 2, 4 and 6 Gy respectively." (PMID 28262749, 2017).
hematoma (1 paper, 2020). A hematoma is a collection of blood from a vascular structure into an extravascular space. "Moreover, the hypoxia-sensitive expression of GAPDH could be demonstrated, which has been described for in vitro cell systems, but has not been previously reported for ex vivo sheep hematoma tissue." (PMID 32260421, 2020).
hilar cholangiocarcinoma (1 paper, 2022). A cholangiocarcinoma that arises from the junction, or adjacent to the junction, of the right and left hepatic ducts. "The ratio of FXR/GAPDH mRNA was significantly different among the hilar cholangiocarcinoma, control and sham operation groups." (PMID 35610302, 2022).
histiocytic lymphoma (1 paper, 2015). "The treatment of U937 cells, which are derived from a human histiocytic lymphoma cell line, with H2O2, inactivates GAPDH via nicotinamide adenine dinucleotide (NAD) depletion." (PMID 26350063, 2015).
hydrocele (1 paper, 2014). "As shown in a scatter diagram, the expression of AQP1/GAPDH was similar between the two cases with hydrocele fluid of less than 10 mL and other cases with more than 100 mL." (PMID 24817884, 2014).
Hyperhidrosis (1 paper, 2025). Abnormal excessive perspiration (sweating) despite the lack of appropriate stimuli like hot and humid weather. "IL-17A expression in sweat gland tissues was upregulated in hyperhidrosis mice but significantly decreased after SR2211 treatment (p < 0.01), while GAPDH served as a loading control." (PMID 41181099, 2025).
Hypoinsulinemia (1 paper, 2014). A decreased concentration of insulin in the blood. "Therefore, the observed reduced fat mass (and implied reduced TAG) in HYP mice is consistent with the hypoinsulinemia, suppressed GAPDH (key glycolysis enzyme) and reported reduced ATP." (PMID 24839967, 2014).
Jaundice (1 paper, 2011). Yellow pigmentation of the skin due to bilirubin, which in turn is the result of increased bilirubin concentration in the bloodstream. "The levels of GAPDH expression were not different between BA patients and controls, between jaundice and jaundice-free group in BA patients, and between those who survived without transplantation and those who survived with transplantation or died." (PMID 21813008, 2011).
lactic acidosis (1 paper, 2024). Metabolic acidosis characterized by the accumulation of lactate in the body. "A further explanation for inhibited glucose consumption during lactic acidosis is the lactate-induced inhibition of the glycolytic glyceraldehyde-3-phosphate dehydrogenase (GAPDH) forward reaction due to elevated NADH concentrations." (PMID 38195466, 2024).
Left ventricular diastolic dysfunction (1 paper, 2022). Abnormal function of the left ventricule during left ventricular relaxation and filling. "W. Nachar found that both GAPDH and HPRT1 were highly stable reference genes in a rabbit model of left ventricular diastolic dysfunction (LVDD)." (PMID 37170359, 2022).
leukocytosis (1 paper, 2017). "Since even the level of leukocytosis did not significantly influence the quantity of human cells (GAPDH-GE), further statistical analyses were based on GAPDH-normalization only." (PMID 28257513, 2017).
leukoplakia (1 paper, 2020). A white patch or plaque on a mucous membrane that cannot be characterized clinically or pathologically as any other disease. "To determine the relative copies of E-Cadherin in leukoplakia samples with different grades of dysplastic features, we first established a standard curve by diluting known concentration of GAPDH gene as described in the methods section." (PMID 32102518, 2020).
Lewis lung carcinoma (1 paper, 2014). "To assess the specificity of our primers, we compared human GAPDH RT-PCR results on RNA extracted from H460-hCD63-GFP cells, murine Lewis lung carcinoma LL2/LLC1 cells, and their respective ELMs." (PMID 25397880, 2014).
liposarcoma (1 paper, 2025). A usually painless malignant tumor that arises from adipose tissue. "In liposarcoma CSC, L-P5, it is observed that expression of GAPDH after the AA treatment is almost equal to C bFGF, while after the DHA treatment, expression is increased compared to the controls." (PMID 41300532, 2025).
liver cysts (1 paper, 2025). "This is the first work presenting the in silico model of two GAPDH isoenzymes from E. granulosus ss/G1, recognized by sera from CE patients with liver cysts." (PMID 41226655, 2025).
lupus nephritis (1 paper, 2019). Glomerulonephritis in the context of systemic lupus erythematosus. "It was also found that the anti-GAPDH autoantibodies were associated with increased serum IgG (r = 0.282, P = 0.001) and IgM (r = 0.177, P = 0.045) levels and decreased incidence of lupus nephritis." (PMID 31049359, 2019).
lysosomal disorder (1 paper, 2019). "In mouse cystinotic PTCs in vivo, the accumulation of CMA substrates (including GAPDH) is caused by mislocalization of LAMP2A, suggesting that CMA may directly affect PTC function in this lysosomal disorder and that LAMP2A trafficking may be affected in these cells." (PMID 30774622, 2019).
macular holes (1 paper, 2017). A hole in the macula of the retina. "Thyroxine-binding globulin, kallistatin, hepatocyte growth factor activator, von Willebrand factor, and glyceraldehyde-3-phosphate dehydrogenase were increased in both PDR versus macular holes and NPDR versus macular holes." (PMID 28452939, 2017).
mantle cell lymphoma (1 paper, 2018). Mantle cell lymphoma is a rare form of malignant non-Hodgkin lymphoma affecting B lymphocytes in the lymph nodes in a region called the ``mantle zone''. "306O13 LNPs also silenced GAPDH (albeit more modestly) in MAVER‐1 cells, a more aggressive human mantle cell lymphoma line, in a dose‐responsive manner." (PMID 30065968, 2018).
metastatic colorectal cancer (1 paper, 2012). "All these data demonstrated that the model of GAPDH, VIL1 and CD45 biomarker combination is a robust method for the detection of CTC from metastatic colorectal cancer patients." (PMID 22304365, 2012).
multinodular goiter (1 paper, 2019). Nodular goiter characterized by more than one discrete tissue mass. "The expression characteristics of 12 candidate reference genes (GAPDH, ACTB, HPRT1, TBP, B2M, PPIA, 18SrRNA, HMBS, GUSB, PGK1, RPLP0, and PGM1) were assessed by qRT-PCR in 45 thyroid tissue samples (15 papillary thyroid carcinoma, 15 paired normal tissues and 15 multinodular goiters)." (PMID 31645594, 2019).
muscular dystrophies (1 paper, 2020). "TRIM32 KO muscles also show a decrease in the glycolytic proteins GAPDH and PyK, just as we observe a reduction in Ald and Pglym levels in tn-/- muscles, suggesting that TRIM32-mediated regulation of glycolysis may be a general mechanism that underlies some muscular dystrophies." (PMID 32223900, 2020).
Myalgia (1 paper, 2020). "Glyceraldehyde-3-phosphate dehydrogenase (GAPDH) is another glycolytic enzyme that was found significantly upregulated in TMD myalgia patients and, like PGK1, is overexpressed in various malignancies and correlates positively with tumor progression." (PMID 32272779, 2020). "In this context, it may be hypothesized that conditions of oxidative stress involved in myalgia may increase the need of PGK1 and GAPDH." (PMID 32272779, 2020).
neuroendocrine tumors of the (1 paper, 2016). "ACTB, CDKN1B, GAPDH, GRB2, RHOA and SDCBP are potent reference genes in neuroendocrine tumors of the lung." (PMID 27802291, 2016). "In the present study, ACTB, CDKN1B, GAPDH, GRB2, RHOA and SDCBP were identified as suitable reference genes in neuroendocrine tumors of the lung." (PMID 27802291, 2016).
non-Hodgkin lymphoma (1 paper, 2015). Distinct from Hodgkin lymphoma both morphologically and biologically, non-Hodgkin lymphoma (NHL) is characterized by the absence of Reed-Sternberg cells, can occur at any age, and usually presents as a localized or generalized lymphadenopathy associated with fever and weight loss. "Moreover, increased expression of GAPDH enhanced aggressiveness and vascularization of non-Hodgkin’s lymphoma." (PMID 26482227, 2015).
nutritional deficiency (1 paper, 2020). "Compared to GAPDH, nutritional deficiency increased the expression of FADS2 8 times (p = 0.004) and necrotic conditions 5 times (p = 0.004)." (PMID 32392704, 2020). "Nutritional deficiency and necrotic conditions also increased the expression of FADS1 2 times compared to B2M (p = 0.004) and 5 times compared to GAPDH (p = 0.004)." (PMID 32392704, 2020).
oncocytic neoplasm (1 paper, 2020). A usually benign neoplasm composed of large cells with abundant eosinophilic granular cytoplasm. "To exclude the possibility of this GAPDH staining pattern being a general feature of oncocytic neoplasms of different organs, we tested a cohort of renal oncocytoma and oncocytic chromophobe carcinoma; none showed this type of staining." (PMID 32365590, 2020).
overnutrition (1 paper, 2015). An imbalanced nutritional status resulting from excessive intake of nutrients. "Maternal peri-conceptional overnutrition, but not food restriction, increased fat mass of postnatal female lambs and glyceraldehyde-3-phosphate dehydrogenase gene expression correlated positively with perirenal fat amount." (PMID 26633942, 2015).
pancreatic (1 paper, 2022). "In this study, we tested the effects of 3-bromo-isoxazoline derivatives specifically designed to bind and inhibit GAPDH activity, in pancreatic ductal-adenocarcinoma cells." (PMID 35804925, 2022).
parasite (1 paper, 2017). "Tpx and GAPDH were confirmed to be associated with the immune responses of hosts against parasite infection and further have proved to have serodiagnostic potential in detection of S. japonicum and Fasciola gigantica." (PMID 29068407, 2017).
plague (1 paper, 2022). Plague is a severe bacterial infection caused by the gram-negative bacterium Yersinia pestis. "For example, EF1α and Arm have been identified as reliable targets for normalizing RT-qPCR data derived from Australian plague locusts under varying rearing density conditions, while GAPDH and UCCR have served as Spodoptera litura reference genes." (PMID 36338494, 2022).
pneumococcal infection (1 paper, 2023). Infections with bacteria of the species streptococcus pneumoniae. "Our previous studies showed that PspA and host GAPDH interactions during pneumococcal infection impacted bacterial localization in the lower airway; specifically, that PspA allowed pneumococci to bind dying epithelial cells in the lungs." (PMID 37982608, 2023).
rectal cancer (1 paper, 2020). A primary or metastatic malignant neoplasm that affects the rectum. "The genes evaluated for rectal cancer and normal rectal samples in our study included GAPDH, RPNI, PUM1, B2M, and PMM1, which are involved in the process of transcription/translation; other genes are involved in nucleotide metabolism, are a part of the cytoskeleton, etc.." (PMID 33457124, 2020).
renal oncocytoma (1 paper, 2020). "None of the renal oncocytomas and oncocytoid chromophobe renal cell carcinomas displayed the aberrant pattern of GAPDH staining for salivary gland Warthin tumors." (PMID 32365590, 2020).
reovirus infection (1 paper, 2023). "The results were normalized to GAPDH levels, as it had stable expression-levels following reovirus infection." (PMID 37753084, 2023).
rhabdomyosarcoma (1 paper, 2025). A rare aggressive malignant mesenchymal neoplasm arising from skeletal muscle. "In the case of rhabdomyosarcoma CSC, Rm-P6, there is nearly equal expression of GAPDH protein in the C bFGF control and the AA and DHA treatments." (PMID 41300532, 2025).
rotator cuff tear (1 paper, 2015). "Although the gene stability data were not provided, GAPDH and ACTB have been used as a reference genes in the study of mRNA regulation in human rotator cuff tear." (PMID 25768100, 2015). "In this study, we assessed the suitability of six reference genes frequently reported in the literature (18S, ACTB, B2M, GAPDH, HPRT1 and TBP) using tendon samples from individuals with and without rotator cuff tear by analyzing gene stability with four software packages." (PMID 25768100, 2015).